ST7-AS1 (ST7 antisense RNA 1)
Synonyms: ST7AS1; ST7OT1
Gene: Long non-coding RNA gene on chromosome 7 (116,952,446 to 116,954,334, reverse strand). Ensembl gene ENSG00000227199.
Diseases named in the same sentence as ST7-AS1 in open-access papers:
ST7-AS1 is named in the same sentence as 1 disease in open-access papers, as found by Europe PMC text mining. Sharing a sentence is not in itself a finding about the gene and the disease.
ST7-AS1 shares sentences with these, for which no sentence is quoted: cancer (1 paper).